IL33 (interleukin 33)
Diseases named in the same sentence as IL33 in open-access papers (continued):
Sharing a sentence is not in itself a finding about the gene and the disease.
food allergy (39 papers, 2012 to 2025). Gastrointestinal disturbances, skin eruptions, or shock due to allergic reactions to allergens in food. "Epithelial-derived cytokines, including thymic stromal lymphopoietin (TSLP) and IL-33 have a pivotal role in the development of allergic response at the gut barrier surface which has been linked to the development of food allergy." (PMID 36660742, 2022). "IL-33 deficient mice have a reduced severity of food-induced reactions, suggesting a potential role of this cytokine in food allergies." (PMID 34943362, 2021). "In fact, mechanical skin injury in AD causes a systemic release of IL-33, leading to the activation of intestinal mast cells and an increase in intestinal permeability, promoting anaphylaxis in patients with AD and food allergies." (PMID 34943362, 2021). "Furthermore, while both IL-33 and IL-10 were independently required for full MC responsiveness during food allergy, IL-10 deficiency further decreased MC responses in ST2-/- mice." (PMID 39935481, 2025). "In a similar vein, we recently also demonstrated a critical role for IL-33 in inducing MC expansion and activation during food allergy development." (PMID 39935481, 2025). "The IL-33/ST2 axis plays a pivotal role in the development of IgE-mediated mast cell (MC) responses during food allergy." (PMID 39935481, 2025). "IL-10 promoted the activation and function of both IgE-activated and IL-33-stimulated MCs, leading to enhanced MC responses during food allergy, passive anaphylaxis, and type 2 inflammation." (PMID 39935481, 2025). "This has been shown to occur through inhibition of Tregs by ILC2s via IL-4 and promotion of mast cell activation in an experimental model of food allergy where expansion of ILC2s was IL-33 dependent." (PMID 39132724, 2024). "TSLP has a critical role in TH2 responses during the sensitization phase of food allergy, while IL-33 is important in inducing IgE-dependent anaphylaxis." (PMID 37628907, 2023). "When stimulated with IL-33, MMC9s increase the production of IL-9 and IL-13 and play a critical role in the pathogenesis of the IgE-mediated food allergy." (PMID 37296626, 2023). "In a mouse model of food allergy, neutralization of all Th2-driving cytokines IL-25, IL-33, and TSLP was necessary to suppress symptoms, but this was not performed in the context of OIT." (PMID 36880703, 2023). "The blocking of IgE in a food allergy mouse model reduces Il-33 expression and the number of intestinal mast cells." (PMID 37296626, 2023). "Innate cytokines that drive type 2 immunity, namely TSLP, IL-33, and IL-25, have also been shown to be necessary for the development of food allergy in mouse models." (PMID 36880703, 2023). "IL-33 has been reported to exacerbate food allergy symptoms by increasing degranulation and survival of mast cells, and induce goblet cell differentiation and MUC2 expression." (PMID 36167830, 2022). "The observed efficacy of anti-IL-33 therapies in clinical trials provides clear evidence that IL-33 is involved in the pathogenesis of food allergy." (PMID 35406669, 2022). "Blocking IL-33 through monoclonal antibodies seems to be a promising therapy not only for AD but also for preventing food allergy development and the progression of the atopic march." (PMID 34943362, 2021). "Exposure of mouse skin to Staphylococcus enterotoxin B (SEB), together with food allergens (soy, ovalbumin or peanut), can induce the Th2 phenotype via IL-33 stimulation of skin-draining DCs and induce food allergy." (PMID 33333859, 2020). "In a murine model of food allergy, IL-33 and MCs promote inflammation in the gastrointestinal tract through IL-4 production by IL-33–stimulated ILC2s, as IL-4 blocks the generation of allergen-specific regulatory T (Treg) cells." (PMID 32226609, 2020).
food allergy (continued). "In another study using mice expressing a gain-of-function mutation of IL-4 receptor α chain (Il4raF709), ILC2s are found to produce some IL-4 in response to IL-33 stimulation in a mouse model of food allergy sensitized with staphylococcal enterotoxin B41." (PMID 27853507, 2016). "Several studies have demonstrated the importance of IL-33 signaling during food allergy." (PMID 39935481, 2025). "We therefore wondered whether the effects of IL-10 on MCs may be regulated by IL-33 signaling and investigated the role of IL-10 on MC activation and function during food allergy development in ST2-/- mice." (PMID 39935481, 2025). "Recently, IL-33 has emerged as a critical mediator of MC responses during food allergy." (PMID 39935481, 2025). "The decrease in body weight after establishing the food allergy model might lead to the downregulation of IL-33 levels in mice fed with the HFD." (PMID 40509380, 2025). "In contrast to these positive markers of food allergy in WT mice and as previously observed by us, ST2-/- animals did not develop allergic diarrhea or exhibit MC-mediated activation, suggesting that the IgE and MC-dependent effects of food allergy require IL-33 signaling." (PMID 39935481, 2025). "As IL-33 plays an important role in food allergic responses following epicutaneous treatment with OVA on the tape-stripped skin, we also investigated whether ST2, a receptor for IL-33, is involved in δ-toxin-mediated food allergy in our model." (PMID 37275864, 2023). "Systemic conditions like food allergy and anaphylaxis also seem to be supported by IL-33." (PMID 38067128, 2023). "Therefore, novel strategies to block ILC2 activation or the IL-33/IL-33 receptor pathway can lead to innovative therapies in the treatment of food allergy." (PMID 37197653, 2023). "IL-33 plays an important role in food allergies since it has been shown that blocking antibodies against IL-33 prevented oral sensitisation to egg whites, and an anti-IL-33 antibody has shown promising results for the desensitisation of peanut-allergic individuals in a phase 2 clinical trial." (PMID 36429158, 2022). "Through an autocrine positive feedback regulation, IL-33 may exacerbate food allergy by promoting mast cell survival and degranulation, and by inducing goblet cell hyperplasia both directly and indirectly." (PMID 36167830, 2022). "Combined treatment with the antagonists of TSLP, IL-25 and IL-33 or with an inhibitor of pro-TH2 cytokine production might be able to suppress established human food allergy." (PMID 34301307, 2021). "Additionally, prevention of food allergy development and suppression of established food allergy by neutralization of IL-33 has been shown." (PMID 31316714, 2019). "In murine models of food allergy, oral exposure to antigen and an adjuvant stimulates gut epithelial cells to express the innate pro-allergenic IL-33, IL-25, and thymic stromal lymphopoietin (TSLP), which contribute to the development of acute reactions to food and promotion of Th2 response." (PMID 31810340, 2019). "In mice, epicutaneous peanut exposure induces cytokine expression dependent on the IL-33-ST2 signaling in DCs and T cells, and resulted in the skin sensitization to the food allergens, suggesting IL-33 may mediate food allergy through skin route in early life." (PMID 29987222, 2018). "The overexpression of the IEC-derived cytokines TSLP and IL-33 is critical in food allergy." (PMID 29896198, 2018). "This is also the first report of Ag-stimulated IL-33 in food allergy." (PMID 23071516, 2012). "Furthermore, while both IL-33 and IL-10 may act as independent variables that regulate MC function during food allergy, these data also point to a potential for synergistic control if it were necessary." (PMID 39935481, 2025).
food allergy (continued). "To further investigate the crosstalk between IL-10 and IL-33, and whether IL-10’s effects on IgE-induced MC responses may depend on IL-33, we assessed the development of food allergy in WT and IL-10-depleted ST2-/- mice using an ovalbumin (OVA)-induced model of intestinal anaphylaxis." (PMID 39935481, 2025). "IgE may not be the only factor determining the severity of the disease, as scientists have discovered the importance of IL-25 and IL-33 in food allergies, and IL-33 has been shown to stimulate Th2 cells, mast cells and ILC2s to promote the type 2 immune response and IgE release." (PMID 34177881, 2021). "To therefore determine the role of the IL-33/ST2 axis in this pathway, we assessed the effects of IL-10 on IgE-mediated MC activation and food allergy development in wild-type (WT) and ST2-/- mice." (PMID 39935481, 2025). "A number of biologics targeting ILC pathways, such as dupilumab (anti IL-4/IL-13 receptor), etokimab (anti-IL-33) and tepezulmab (anti-TSLP) have been trialled in food allergy and other atopic diseases [54▪,58,59]." (PMID 39132724, 2024). "The epithelial cell-derived cytokines IL-33, IL-25, and TSLP are central regulators of type 2 immunity, which promotes a wide array of allergic responses, including food allergies." (PMID 36429158, 2022). "The upstream role of IL-33 and TSLP in promoting Th2 responses makes them interesting targets for the treatment of atopic conditions, including food allergy." (PMID 34456900, 2021). "In a food allergy mouse model, TSLP participates in the skin sensitization to food antigens, promoting basophil recruitment and initiating Th2 responses, whereas IL-33 is essential for gut-mediated sensitization and effector responses, including anaphylaxis." (PMID 34456900, 2021). "In short, activation of ILC2s by local epithelial cytokines IL-33 and TSLP has been shown to play a major role in the development of food allergy." (PMID 33333859, 2020). "In mice it was proven that only a cocktail of the three monoclonal antibodies against IL-25, IL-33, and TSLP can inhibit the development of food allergy in mice." (PMID 33333859, 2020). "Activation of the NF-ĸB signaling pathway and release of epithelium-derived IL-33, TSLP, and IL-25 are observed in airway epithelium during the initiation of type 2 immune response in respiratory mucosa and in food allergy." (PMID 31810340, 2019). "Our data demonstrate that IL-10 enhances MC responses in both WT and ST2-/- mice, suggesting that IL-33 signaling is not required for IL-10’s effects either during IgE-mediated MC activation or food allergy." (PMID 39935481, 2025). "We have generated foundational data that could lead to additional therapies for food allergy in patients with AD by targeting S. aureus skin colonization, CD40, IL-33, basophils, and IL-4 signaling." (PMID 41005294, 2025). "In this study, we demonstrate that IL-10 is able to regulate IgE-mediated MC proliferation and activation as well as MC responses during food allergy even in the absence of IL-33 signaling, suggesting that IL-33 is dispensable for IL-10’s effects." (PMID 39935481, 2025). "Etokimab, an antagonist of IL-33, has been recently studied for IgE-mediated peanut allergy, while no clinical trials with tezepelumab in food allergy have been reported." (PMID 37628907, 2023). "Although information of direct induction of the production of IL-33 and TSLP by food allergens is sparse to date, several food allergens display proteolytic activity, and the role of these cytokines in the development food allergies is well established." (PMID 36660742, 2022). "Study of the MC response to IL-33 by FACS was possible in the spleen however, where MCs may also become activated and increased during inflammation, as reported in food allergy and sepsis." (PMID 31919358, 2020).
food allergy (continued). "In another study using a food allergy mouse model, blockade of IL-25, IL-33, or TSLP did not suppress established food allergies, and optimal food allergy suppression required treatment by combined blocking of all three cytokine signals." (PMID 32309281, 2020). "Furthermore, these findings represent a new conceptual paradigm by linking atopic status (IL-4), dietary antigen and IgE/FcεR complex interactions, and inflammatory cues (exemplified by IL-33) with MMC9 biology and food allergy." (PMID 27853507, 2016). "Food allergy induction in epicutaneously sensitized mice or mice with alterations in IL-4 signaling was attenuated in ST2-/- mice, suggesting that IL-33-mediated signals are critical for the development of oral anaphylaxis in mice, and that IL-33 promotes food anaphylaxis by targeting MCs or ILC2s." (PMID 39935481, 2025). "Other currently investigated drugs with significantly less evidence in the area of food allergies are dupilumab, the anti-IgE antibody ligelizumab (currently in a phase III trial for peanut allergy), agammaglobulinemia TKI acalabrutinib (completed phase II) and etokimab (anti-IL-33 antibody)." (PMID 39600395, 2024).
cardiac hypertrophy (37 papers, 2013 to 2025). "Previous research has demonstrated that the early and substantial release of interleukin-33 (IL-33) following ischemic-reperfusion AKI is associated with long-term cardiac hypertrophy and dysfunction." (PMID 39678250, 2024). "The binding of sST2 to IL-33 has been associated with myocardial hypertrophy and fibrosis by blocking." (PMID 35877052, 2023). "Under physiological conditions, IL-33/ST2L signaling inhibits cardiac hypertrophy and fibrosis, contributing to myocardial protection." (PMID 40723060, 2025). "sST2 is a decoy receptor that inhibits the beneficial cardioprotective effects of Interleukin-33, thus contributing to cardiac hypertrophy, myocardial fibrosis, and in the final phase to HF." (PMID 39796029, 2024). "By binding IL33, sST2 acts as a decoy receptor and removes the protective effects of IL33 against cardiac hypertrophy, reduction of contractility, and fibrosis." (PMID 37600055, 2023). "The IL-33/ST2L signaling pathway is a mechanically activated system that inhibits cardiac hypertrophy and fibrosis." (PMID 35224046, 2022). "The ST2L also represents the receptor for IL-33, exercising cardioprotective actions through binding, such as inhibiting myocardial fibrosis, limiting ventricular hypertrophy, and preventing early apoptosis." (PMID 35888173, 2022). "In pressure-overload murine model, deletion of ST2 enhanced myocardial fibrosis and cardiac hypertrophy, suggesting a potential role for IL-33/ST2 signaling axis in cardiac remodeling under mechanical overload." (PMID 35479285, 2022). "In mice, IL-33/ST2 signal activation can effectively control myocardial hypertrophy and cardiac fibrosis." (PMID 36291105, 2022). "On the contrary, sST2 removes IL-33 from the circulation, promoting cardiac hypertrophy, fibrosis, and ventricular dysfunction." (PMID 34422136, 2021). "The interaction of ST2L and IL-33 can mitigate cardiac hypertrophy and myocardial fibrosis, thereby exerting protection on the myocardium." (PMID 34422136, 2021). "sST2 competes with lST2 to bind with interleukin-33 (IL-33), which is involved in ameliorating myocardial hypertrophy and fibrosis in response to cardiovascular stretch." (PMID 33282418, 2020). "It has been reported that the activation of ST2L has an anti-NF-κB effect, as in cardiomyocytes; IL-33-activated NF-κB inhibits angiotension II-induced NF-κB activation, thus alleviating the cardiac hypertrophy." (PMID 33344656, 2020). "Gene ablation of IL-33 or ST2 has demonstrated that the IL-33/ST2 signaling pathway is crucial for reducing cardiac hypertrophy, ventricular chamber dilation, and cardiac fibrosis under mechanical stress." (PMID 30761134, 2019). "It has been demonstrated that IL-33 interacts with its receptor ST-2L and plays antihypertropic effect in the pressure overload-induced myocardial hypertrophy through modulating the NFκB." (PMID 23457506, 2013). "Angiotesin II or phenylephrine favour cardiac hypertrophy by inducing NF-kB action: IL-33, by interacting with ST2L, is able to attenuate NF-kB promoter activity and the phosphorylation of IKK." (PMID 24335613, 2013). "When circulating levels of sST2 are aberrantly augmented, the tight binding of sST2 to IL-33 results in the deactivation of ST2L/IL-33 and contributes to pro-fibrotic and pro-apoptotic signaling and ultimately leads to interstitial cardiac fibrosis and myocyte hypertrophy." (PMID 39444690, 2024). "The complex ST2L/IL-33 has a cardioprotective effect, limiting cardiomyocyte apoptosis, fibrosis and cardiac hypertrophy, whereas sST2 acts as a decoy receptor for IL-33, preventing its beneficial effects and leading to cardiac fibrosis, ventricular remodeling and negative cardiac outcomes." (PMID 39200768, 2024).
cardiac hypertrophy (continued). "Inhibition of the interaction between IL-33 and tST2 leads to a reduction of myocardial fibrosis, cardiomyocyte hypertrophy, and apoptosis, while sST2 removes IL-33 from the circulation, promoting cardiac hypertrophy, fibrosis, and ventricular dysfunction." (PMID 37109127, 2023). "sST2 blocks the action of IL-33, which leads to myocardial hypertrophy." (PMID 35224046, 2022). "The indirect resistance to IL-33 might activate adverse cardiac hypertrophy and remodeling through lymphocyte function." (PMID 32886697, 2020). "IL-33 levels were found to be significantly elevated upon a cyclic stretch of cardiac fibroblasts in vitro, and the administration of IL-33 was shown to inhibit myocyte amino acid incorporation and growth thus protecting against cardiac hypertrophy." (PMID 30405626, 2018). "IL-33 signaling is protective against cardiac fibrosis and hypertrophy." (PMID 28704488, 2017). "Moreover, IL-33 administration reduced ventricular hypertrophy and fibrosis and improved the survival rate in the control mice but not in ST2-deficient mice." (PMID 23936023, 2013). "For example, in the heart, IL-33 has been shown to antagonize angiotensin II- and epinephrine-induced cardiomyocyte hypertrophy, and ST2-knockout mice exhibit increased ventricular hypertrophy, more severe fibrosis, and impaired survival." (PMID 39925809, 2025). "Its ligand is represented by IL-33, and the IL-33/ST2 interaction has a protective effect against fibrosis and myocardial hypertrophy." (PMID 38203459, 2023). "By acting as a circulating decoy for interleukin-33 (IL-33), it prevents the cardioprotective effects of the ST2/IL-33 signaling, thus promoting maladaptive myocardial hypertrophy and cardiomyocyte apoptosis." (PMID 36088327, 2022). "Myocardial hypertrophy and fibrosis were observed in ST2-knockout mice, and recombinant IL-33 exerted protective effects on cardiac cells." (PMID 36291105, 2022). "IL-33/ST2L signaling exerts a cardioprotective effect and protects the myocardium from hypertrophy and myocardial fibrosis after pressure overload." (PMID 34631895, 2021). "IL-33 has an anti-hypertrophic effect, whereas sST2 can competitively inhibit the IL-33/ST2 pathway and promote cardiac hypertrophy and fibrosis." (PMID 34026868, 2021). "The pathophysiology of this observation may explained by the attenuation of interleukin-33/ST2 cardioprotective properties, leading to maladaptive myocardial hypertrophy and fibrosis." (PMID 38678167, 2024). "Likewise, the functional ligand of ST2 (interleukin-33; IL-33) is released from cardiac fibroblasts in response to damage, and its interaction with ST2L mediates a cardioprotective mechanism that counteracts cardiac hypertrophy and fibrosis, reduces apoptosis, and improves myocardial function." (PMID 35780161, 2022).